MTOR (mechanistic target of rapamycin kinase)
Diseases named in the same sentence as MTOR in open-access papers (continued):
Sharing a sentence is not in itself a finding about the gene and the disease.
ischemia (continued). "Under basal conditions, the activity of the MTOR (mechanistic target of rapamycin kinase) complex suppresses autophagy induction, but autophagy is triggered by various conditions, such as starvation, inflammation, and ischemia, through the downregulation of the MTOR complex." (PMID 39099167, 2024). "In the retina of mice subjected to ischemia, 48 h fasting reduced the phosphorylation of 4EBP1 (Thr37/46) observed after 24 h reperfusion suggesting that, at this time point, a low mTOR activation state was maintained in the ischemic retina of fasted mice as compared with fed." (PMID 30250019, 2018). "The study by Huang and co-workers demonstrated that crocin (the chemical found in saffron flowers) induces anti-ischemia in MCAO rats and inhibits autophagy by regulating mTOR." (PMID 34362425, 2021). "DADLE-evoked DOR activation enhanced neuronal autophagy through activating the AMPK/mTOR/ULK1 signaling pathway to improve neuronal survival and exert neuroprotective effects against ischemia." (PMID 32549974, 2020). "Since it has been shown that the inhibition of mTOR by rapamycine elicits cardioprotective effect in vivo, and that RIC, while protecting the myocardium against ischemia, downregulates mTOR." (PMID 26581389, 2015). "During ischemia, it activates AMPK and inhibits mTOR, thereby increasing cytoprotective autophagy, while during reperfusion, ALDH 2 inhibits AMPK and activates Akt, thereby activating mTOR,inhibiting AkT-dependent autophagy." (PMID 37728583, 2024). "The kidneys of trehalose-treated rats displayed higher LC3-I and LC3-II levels compared to vehicle-treated rats following 60 min of ischemia and 24 h of reperfusion, without affecting phosphorylated S6, suggesting no change in the mTOR activity and apoptosis." (PMID 33003356, 2020). "Since the myocardial content of both forms of mTOR increased, no significant change in the phospho-to-total mTOR ratio occurred during ischemia." (PMID 24949720, 2014). "However, the effects of mTOR inhibition on brain pericyte contraction and death during ischemia have not yet been investigated." (PMID 39331260, 2025). "For example, in myocardial ischemia and reperfusion, autophagy protects the myocardium during ischemia by ensuring energy use, engulfing damaged mitochondria and reducing oxidative stress, triggered by AMPK activation and mammalian target of rapamycin (mTOR) inhibition." (PMID 39010053, 2024). "Thus, the increased mRNA levels of insulin receptor (Insr) observed in both renin-b-overexpressing H9c2 cells have the potential to initiate the activation of the PI3K/AKT/mTOR signaling cascade, resulting in AKT-mediated cardioprotective effects during ischemia-related conditions." (PMID 35563765, 2022). "Therefore, the maintenance of the upregulated autophagy flux observed in the early phase of reperfusion takes place in the absence of mTOR inhibition and might rely on different molecular events or representing the final part of the autophagy wave triggered by ischemia." (PMID 30250019, 2018).
rheumatoid arthritis (72 papers, 2015 to 2025). A chronic, systemic autoimmune disorder characterized by inflammation in the synovial membranes and articular surfaces. "From the perspective of experimental modeling, the most consequential alterations in the functional properties of fibroblast-like synoviocytes (FLSs) in rheumatoid arthritis (RA) are closely linked to the dysregulation of the PI3K/Akt/mTOR signaling pathway." (PMID 40872543, 2025). "Additionally, mTOR activation in CD8+ T cells from rheumatoid arthritis patients was identified, and it was positively linked with the severity of the condition." (PMID 36737819, 2023). "In rheumatoid arthritis, the mTOR pathway inhibits synovial fibroblast ferroptosis by increasing GPX4 expression." (PMID 40140647, 2025). "Background/Objectives: Constitutive activation of the PI3K/AKT/mTOR signaling cascade underlies the aggressive phenotype of fibroblast-like synoviocytes (FLSs) in rheumatoid arthritis (RA); however, a quantitative synthesis of in vitro data on pathway inhibition remains lacking." (PMID 40872543, 2025). "Over recent years, a variety of mTOR inhibitors have been developed and entered clinical trials for targeted therapy in tumors, organ transplantation, rheumatoid arthritis and other diseases." (PMID 38476632, 2024). "In this study we explored the role of the mTOR pathway on Rheumatoid Arthritis synovial fibroblast (RASF) metabolism and activation and determined if crosstalk with the Hippo-YAP pathway mediates their effects." (PMID 36817783, 2023). "SLC7A5, as an amino acid transporter, participates in cell invasion and regulates the protein levels of MMP3 and MMP13 through mTOR signaling in rheumatoid arthritis fibroblast-like synovial cells." (PMID 35785145, 2022). "In total, we found that D3R on mast cells alleviated inflammation in mouse rheumatoid arthritis through the mTOR/AKT/AMPK-LC3-ubiquitin-TLR4 signaling axis." (PMID 35292659, 2022). "Inhibition of mTOR by everolimus has shown moderate efficacy in reducing joint inflammation in rheumatoid arthritis patients." (PMID 34065644, 2021). "Inhibiting the mTOR pathway clearly improves the symptoms of rheumatoid arthritis, multiple sclerosis, autoimmune encephalomyelitis, and other animal models." (PMID 32318017, 2020). "The mTOR inhibitors (rapamycin and its analogs) had been used in the treatment of diseases such as solid tumors, organ transplantation, and rheumatoid arthritis." (PMID 32908897, 2020). "Animal studies have also corroborated that rapamycin-dependent mTOR inhibition is effective for various diseases, including ischemic stroke, rheumatoid arthritis, and EAE." (PMID 33613560, 2020). "Curcumin, another inhibitor of mTOR signaling, was also reported to alleviate rheumatoid arthritis-induced inflammation and synovial hyperplasia by reducing inflammatory mediators like IL-1β, TNF-α, MMP-1, and MMP-3." (PMID 32867828, 2020). "Intracellular signaling pathway (including mTOR signaling) play a critical role in rheumatoid arthritis." (PMID 31608109, 2019). "The technique has been used previously for testing immunosuppressive drug responses in patients with rheumatoid arthritis and for the monitoring of mTOR inhibitor therapy." (PMID 29123208, 2017). "It has been demonstrated in transgenic mice, bearing human-TNFα to resemble a rheumatoid arthritis model, that mTOR signaling drives OC function, and that inhibition of this pathway can mitigate bone erosion." (PMID 26468083, 2015). "In the present study, a comprehensive and quantitatively substantiated analysis of the role of PI3K/AKT/mTOR inhibition in regulating the pathological properties of human fibroblast-like synoviocytes in rheumatoid arthritis has been undertaken for the first time." (PMID 40872543, 2025).
rheumatoid arthritis (continued). "In addition, Notch signalling has also been reported to drive mTOR activation by fibroblasts cells in rheumatoid arthritis, and T cells in vasculitis." (PMID 39271773, 2024). "The PI3K/AKT/mTOR signaling pathway is significantly activated in rheumatoid arthritis." (PMID 32660056, 2020). "Thus, the metabolic checkpoint kinase mTOR regulates the synovial tissue response to inflammation in rheumatoid arthritis (RA)." (PMID 29768212, 2018). "Intriguingly, research in rheumatoid arthritis (RA) has revealed that Semaphorin 5A in RA synovial fluid curtails ferroptosis in RA synovial fibroblasts by tweaking the PI3K/AKT/mTOR axis to boost GPX4 levels." (PMID 40586853, 2025). "Thus pharmacological inhibition of mTOR might inhibit the quasi-programmed endochondral ossification that, as argued here, is the main pathogenetic process in OA in humans; in clinical trials, mTOR inhibitors have been shown to inhibit rheumatoid arthritis." (PMID 40381687, 2025). "Compound 2 was demonstrated to reduce the progression of rheumatoid arthritis (RA) by suppressing the Akt/mTOR and NF-κB signaling pathways." (PMID 41373781, 2025). "During rheumatoid arthritis (RA) pathogenesis, miR-137 is downregulated in association with the REST/mTOR axis, which is negatively correlated with inflammatory factors." (PMID 38138985, 2023). "Feng and Qiu investigated how ART affects chondrocyte proliferation, apoptosis, and autophagy in the rheumatoid arthritis (RA) rat model through the PI3K/AKT/mTOR signalling pathway." (PMID 35335880, 2022). "In this study, we analyzed how circFADS2 was regulated in LPS-treated chondrocytes and isolates from Rheumatoid arthritis (RA) patients and found that circFADS2 and mTOR were highly expressed whereas miR-498 expression was significantly reduced." (PMID 31141496, 2019). "This approach has been used to create detailed signaling maps for epidermal growth factor (EGF) receptor (EGFR), mechanistic target of rapamycin (mTOR), Rb/E2F pathway, toll-like receptor signaling, and comprehensive molecular interaction maps for budding yeast cell cycle and rheumatoid arthritis." (PMID 30456354, 2018). "Another research study has shown that DIM suppressed the proliferation, migration, and invasion of rheumatoid arthritis (RA) fibroblast-like synoviocytes (FLSs) and MAPK/AKT/mTOR pathways, thereby preventing knee joint inflammation." (PMID 40094833, 2025). "BMSC-derived exosomes were reported to inhibit ROS/NLRP3 inflammasomes through AMPK/mTOR/autophagy signaling, and AMPK/mTOR/ULK-1 signaling has been shown to ameliorate rheumatoid arthritis." (PMID 38987770, 2024). "WTD attenuates rheumatoid arthritis by inhibiting angiogenesis and regulating the PI3K/AKT/mTOR/HIF-1α pathway." (PMID 37221510, 2023). "The mTOR/AKT/AMPK-LC3-ubiquitin signaling axis takes part in this process that bridges mast cell activation and TLR4 degradation in rheumatoid arthritis." (PMID 35292659, 2022). "Pharmacology, pharmacokinetics, clinical efficacy, safety, and role of tocilizumab in rheumatoid arthritis (RA) are well-established and possibly due also to its effect on the AKT/mTOR pathway." (PMID 32398164, 2020). "In addition to SpA synovial tissue, we also stained synovial tissue from rheumatoid arthritis (RA) patients, as the presence of pS6 and the expression of mTOR pathway have previously been described in RA synovitis." (PMID 32194539, 2019). "Inhibition of mTOR has been demonstrated to halt osteoclastogenesis and to improve joint erosions in a TNF-transgenic mice model of rheumatoid arthritis." (PMID 32194539, 2019). "Our results define a critical role for mTOR in the regulation of the pro-inflammatory response in FLSs and unfold its pathogenic involvement in TNF-driven diseases, such as rheumatoid arthritis (RA)." (PMID 29768212, 2018). "It is proposed that miR-125 could attenuate rheumatoid arthritis (RA) and regulate the PI3K/Akt/mTOR signaling pathway." (PMID 37834215, 2023).
rheumatoid arthritis (continued). "While the effectiveness of galangin has been previously demonstrated in the treatment of RA, the present study aimed to investigate the potential mechanism of galangin in LPS-treated rheumatoid arthritis fibroblast-like synovial cells (RAFLSs) in vivo in terms of the mTOR/PI3K/AKT signaling pathway." (PMID 35485325, 2022). "Importantly, we showed that T cells from rheumatoid arthritis patients failed to modulate both ERK signaling and the AKT/mTOR pathway upon PD-L1 engagement." (PMID 33901179, 2021). "Importantly, T cells from rheumatoid arthritis patients exhibited high basal levels of phosphorylated ERK and following PD-L1 cross-linking both ERK signaling and the AKT/mTOR/S6 pathway failed to be down modulated, making them refractory to the acquisition of a regulatory phenotype." (PMID 33901179, 2021).
brain tumors (71 papers, 2011 to 2025). "The limited number of approved inhibitors for clinical application can be attributed to toxicities associated with PI3K/mTOR inhibitors and their limited activity in the CNS, particularly in the context of brain tumors, and development of resistance." (PMID 40386392, 2025). "Since PI3K–Akt–mTOR axis abnormalities are implicated in the etiology of GBM and other types of brain tumors, the activation of the mTOR pathway in the CNS is a subject of intense research." (PMID 35159037, 2022). "Aberrant mTOR signaling is a hallmark of several neurological disorders—collectively termed “mTORopathies”—including genetic syndromes, cortical malformations, and brain tumors." (PMID 41301687, 2025). "Previous studies have demonstrated clear communication between YB-1 and the PI3K/AKT/mTOR pathway and thus this finding may indicate a similar association within paediatric brain tumours." (PMID 36831428, 2023). "We then asked whether oncogenic IDH1 might be associated with markers of mTOR activation in human brain tumours." (PMID 27624942, 2016). "Interestingly, another brain tumor that also demonstrates this molecular signature of mTOR activation is TSC-associated SEGA." (PMID 23717811, 2013). "Unfortunately, mutations, amplifications, or deletions in genes related to mTOR or its complexes (mTORC1 and mTORC2) change the functioning of the mTOR signaling pathway and lead to uncontrolled cell proliferation, avoidance of apoptosis, and the development of neoplasms, including brain tumors." (PMID 39410026, 2024). "We summarize the mechanisms underlying autophagy dysregulation in GBM, including PI3K/AKT/mTOR signaling, which is most active in brain tumors, and EGFR and mutant EGFRvIII." (PMID 39195222, 2024). "Analogs of Rapa such as everolimus are used as therapeutic drugs to treat patients with TSC to inhibit the growth of kidney and brain tumors, and topical mTOR inhibitors have been shown to be effective in treating skin abnormalities." (PMID 39187374, 2024). "mTOR pathway activation is thought to be one of the main mechanisms of resistance in BRAF V600E-mutant brain tumors following targeted treatment." (PMID 35159037, 2022). "Guided by a clinical perspective, we chose the potent mTOR inhibitor RL1 as drug candidate with high anti-brain tumor efficacy but missing knowledge on its effectivity on GSCs." (PMID 34575669, 2021). "mTOR inhibitors are currently under clinical testing for many cancer types, including pediatric brain tumors." (PMID 34673573, 2021). "mTOR represents a hallmark-signaling pathway in GBM and there is a strong rationale for its therapeutic targeting in this aggressive brain tumor." (PMID 34944625, 2021). "Because of the deficiency of Tsc2, the activity of the Tsc1/Tsc2 complex is decreased, leading to the overactivation of the mTOR pathway, which is the primary cause of TSC-related symptoms, including tumours of the brain, skin, heart, lungs, and kidney." (PMID 34576223, 2021). "Brain tumor-initiating cells transport tenascin-C through exosomes, which interacts with integrin α5β1 and αVβ6 to inhibit the mammalian target of rapamycin (mTOR) signaling pathway and further inhibit T cell activity." (PMID 34588957, 2021). "Various inhibitors of mTOR and/or PI3K/AKT can suppress the OCT4/mTOR axis in malignant brain tumors." (PMID 33585252, 2020). "Several mTOR inhibitors have already been approved or are currently undergoing clinical trials, making mTOR inhibition a very promising therapeutic avenue for MYCN-deregulated brain tumors." (PMID 33585252, 2020). "The positive outcome of the present case suggests considering this approach for patients with RASopathies and brain tumors with hyperactivated MTOR signaling." (PMID 32806529, 2020). "A recent study reported that both sporadic and syndromic brain tumors are related to hyperactivation of mTOR." (PMID 31665029, 2019).
brain tumors (continued). "mTOR inhibitors have been used to treat subependymal glioma (SEGA) that is a brain tumor characteristic of TSC." (PMID 30467464, 2018). "We found that the mTOR-pathway was activated in both human low grade brain tumors such as SEGAs, diffuse gliomas and malignant primary and secondary brain tumors." (PMID 25993328, 2015). "Our study showed that oncogenic KRAS promoted brain tumors in zebrafish, and that tumorigenesis was driven by the activation of the canonical Ras and mTOR pathways." (PMID 25644510, 2015). "For example, inactivation of Akt-mammalian target of rapamycin (mTOR) signaling is responsible for the parallel occurrence of autophagy and apoptosis in human brain tumor cells exposed to hydrogen peroxide." (PMID 23841076, 2013). "Altogether, these findings establish mTOR as a key mediator of tumor-induced neurological dysfunction and highlight its translational potential as a target for restoring circuit level function in brain tumors." (PMID 41301687, 2025). "Same in brain tumour, hypoxia induced mTOR‐mediated PGK1 acetylation to induce autophagy." (PMID 40534132, 2025). "Reports suggest that sensory signals, such as visual or olfactory stimulation, may influence the development and behavior of brain tumors, potentially through signaling pathways such as mammalian target of rapamycin (mTOR) signal." (PMID 38720342, 2024). "In MYCN-driven human brain tumor models generated from primary embryonic or induced pluripotent stem cell (iPSC)-derived neural stem cells we could show a significant correlation of mTOR pathway activation and OCT4 levels." (PMID 33585252, 2020). "Additionally, in the context of brain tumors, targeting mTOR activation is considered a potent therapeutic avenue." (PMID 33371210, 2020). "Moreover, the mTOR inhibitor rapamycin improved the antitumor effect of the hTERT-driven oncolytic adenovirus OBP-405 with modified fibers against brain tumor cells via enhanced autophagy." (PMID 32637577, 2020). "Simultaneously inhibiting mTOR and glutamine metabolism suppressed brain tumor proliferation." (PMID 31011190, 2019). "Overview of a selection of clinical trials targeting the mTOR-pathway in brain tumor patients." (PMID 25993328, 2015). "The PI3K/Akt/mTOR axis is also activated in a substantial percentage of pediatric brain tumors." (PMID 23717811, 2013). "In this way, Toll-like receptor (TLR), PI3K/Akt/mTOR, MAPK/ERK, NOTCH, and other signaling pathways have recently become some of the main signaling pathways in brain tumors." (PMID 40727443, 2025). "It is also worth mentioning that dual PI3K/mTOR inhibitors exert anticancer effects and can be considered for the treatment of SEGA brain tumors." (PMID 39410026, 2024). "miR-17-5p regulates PI3K/AKT/mTOR and RAS/MAPK/ERK genes and is directly correlated with tumor stage and aggressiveness of pediatric brain tumors." (PMID 34769348, 2021). "RapaLink-1, a bivalent third generation mTOR inhibitor, which combines rapamycin with INK128 (Sapanisertib) by an inert chemical linker, has also shown great efficacy in MYCN-driven brain tumor models." (PMID 33585252, 2020). "The OCT4/mTOR axis correlated with poor prognosis in SHH MB patients and OCT4-overexpression increased the malignancy of these pediatric brain tumors." (PMID 33585252, 2020). "The mTOR inhibitors, in particular, AZD8055, not only significantly suppressed brain tumor growth but also prolonged the integrity of the intracranial blood brain barrier." (PMID 30337536, 2018). "There are studies showing that combining rapamycin, an mTOR inhibitor, with an EGFR inhibitor improves the clinical outcome in a small number of patients with recurrent GBM brain tumor." (PMID 27788487, 2016). "Therefore mTOR-targeted therapies might be a useful strategy for brain tumor patients." (PMID 25993328, 2015). "In low-grade adult brain tumors, activation of the PI3K/mTOR pathway portends shorter overall survival." (PMID 23717811, 2013).